GRIA2 (glutamate ionotropic receptor AMPA type subunit 2)
Diseases named in the same sentence as GRIA2 in open-access papers (continued):
Sharing a sentence is not in itself a finding about the gene and the disease.
psychosis (5 papers, 2020 to 2025). "GRIA2, in turn, has been widely implicated in psychotic disorders, including SCZ and BD, and its expression is reduced by certain antipsychotic treatments." (PMID 40943654, 2025). "Levels of EV-secreted miRNA-223 were increased in the orbitofrontal cortex of post-mortem brain samples from patients with SCZ and patients with BD with psychosis, and an inverse association was observed with the expression of the targets of miRNA-223, GRIN2B and GRIA2." (PMID 36302978, 2023). "Here we show that miR-223, a known exosome-enriched miRNA, is significantly increased in the OFC of subjects with SCZ and BD with psychosis, and is negatively correlated to the mRNA levels of its targets GRIN2B and GRIA2, which are also significantly downregulated." (PMID 31775160, 2020). "Our results showed that BD patients with psychosis but not BD patients without psychosis displayed significant increases in SERPINA3, and reductions in GRIN2B, GRIA2, and ADAR2 mRNAs, similar to those seen in SCZ." (PMID 31775160, 2020).
Rett syndrome (5 papers, 2019 to 2022). A severe neurodevelopmental disorder affecting the central nervous system. "GRIA2 is implicated in ID and ASD, and recently, 20 heterozygous de novo GRIA2 variants were identified in 28 individuals with ID, ASD, and Rett syndrome-like features as well as seizures or DEE, suggesting that a defective GluA2 leads to NDD." (PMID 35457207, 2022).
brain tumors (4 papers, 2016 to 2024). "First, two ionotropic AMPA receptors, GRIA1 and GRIA2 were found to be higher expressed in primary brain tumors." (PMID 38835368, 2024).
alcohol (3 papers, 2014 to 2023). "For instance, in the BLA, we found that individuals with AUD were more likely to have an exon skipping event of the GRIA2 flip exon (exon 14), which is associated with longer glutamate receptor opening and consistent with the BLA pathology in alcohol use46–48." (PMID 36894673, 2023).
breast cancer (3 papers, 2014 to 2022). A primary or metastatic malignant neoplasm involving the breast. "To further validate the identified target genes that showed significant changes in DE and DM patterns in response to maternal BSp treatment, we evaluated gene expression of Avpr2, Cyp4a12b, Dpp6, Gria2, Pcdh9 and Tspan11 genes in the offspring mammary tumors using qRT-PCR." (PMID 35263365, 2022). "Among those are the ionotropic glutamate receptor AMPA type subunit 2 (GRIA2) and the γ-aminobutyric acid receptor type A (GABAAR) in brain metastases of melanoma and breast cancer, respectively." (PMID 27618016, 2016). "Expression of GRIA2 and GRIA3 mRNA was induced by hypoxia in Hep3B cells but not in two breast cancer cell lines." (PMID 25326682, 2014).
cognitive decline (3 papers, 2014 to 2021). "Furthermore, miR-30b, miR-186-5p, and miR-218 have also been reported to bind Gria2 3′-UTR and their overexpression have been associated with a decrease in GluA2 levels regulating synaptic function and cognitive decline in AD experimental models." (PMID 33435363, 2021).
Dystonia (3 papers, 2021). An abnormally increased muscular tone that causes fixed abnormal postures.
endometrial cancer (3 papers, 2020 to 2023). Primary or metastatic malignant neoplasm involving the endometrium (mucous membrane that lines the endometrial cavity). "In endometrial cancer (EC), GluR2 (GRIA2) expression was up-regulated, and the GluR2 antagonist effectively suppressed the invasion, migration and proliferation of tumor cells." (PMID 33969375, 2021). "Highly expressed GRIA2 was also expressed in EC cell lines (especially in Ishikawa cells), indicating that it might play an important role in endometrial cancer and nerve crosstalk." (PMID 32201522, 2020).
mental disorder (3 papers, 2015 to 2023). A disease that has its basis in the disruption of mental process. "Stage T3 was also enriched for nervous system development (FDR = 6 × 10–12; e.g., ERBB4) and projection morphogenesis (FDR = 1 × 10–9; e.g., SEMA6D), and was most specifically marked by GRIA2, a glutamate ionotropic receptor subunit implicated in multiple mental disorders." (PMID 36865235, 2023). "Possible implications of an altered editing efficiency at the R/G site in GRIA2 in mental disorders in human and mouse were recently observed." (PMID 26024316, 2015).
microcephaly (3 papers, 2021 to 2022). A congenital or acquired developmental disorder in which the circumference of the head is smaller than normal for the person's age and sex. "Thus, the growth retardation phenotype may be associated with NAA15 duplication, speech delay with GRIA2 and microcephaly with PLK4 duplication." (PMID 35185781, 2022).
migraine (3 papers, 2015 to 2024). "The particular editing function of ADARB1 upon the AMPA glutamate receptor subunit (GRIA2) pre-mRNA makes the investigation of ADARB1 in migraine interesting, because glutamate is a major mediator in the CNS and its regulation has been studied as a possible mechanism causing migraine." (PMID 25916332, 2015).
neuroblastoma (3 papers, 2013 to 2021). Neuroblastoma (NB) is the most common solid, extracranial childhood tumor. "PMOs were assessed for their AluJ cassette skipping efficiencies, and were tested for their effects on Q/R site editing in a heterologous cell model (HeLa) and in human neuroblastoma cell lines endogenously expressing GRIA2 RNA for the GluA2 subunit (SH-SY5Y)." (PMID 34536489, 2021). "The nuclear respiratory factor 1 (NRF-1) is a transcription factor that was also shown to regulate Gria2 gene transcription in neuroblastoma cells." (PMID 23389038, 2013). "To determine whether LEDGF is functionally involved in the regulation of Gria2 flip/flop splicing, we tested the effect of knockdowning LEDGF on flip/flop ratio in a neuroblastoma cell line, Neuro-2A, using a Gria2 minigene." (PMID 27352031, 2016).
Sepsis (3 papers, 2023 to 2025). Sepsis is defined as life-threatening organ dysfunction caused by a dysregulated host response to infection. "A missense site p.M620V in Grik2 and a 3′UTR site in Gria2 showed differential editing during sepsis." (PMID 39135964, 2024). "In Astrocyte 1, inflammation-associated genes (GFAP, FOS, C3, CD74) were significantly upregulated, while BBB-related genes (GRIA2, NRGN, TXNIP) were downregulated in sepsis." (PMID 41030458, 2025).
atherosclerosis (2 papers, 2021). A disease characterized by the build-up of fatty material and calcium deposition in the arterial wall resulting in partial or complete occlusion of the arterial lumen. "By screening, GSE23314 and GSE53274 were chosen, and through the analysis of the two datasets, we discovered significant differences in GRIA2 expression in restenosis and atherosclerosis tissues." (PMID 34504438, 2021). "GRIA1 and GRIA2 mRNA levels correlated positively with the inferred relative abundance of VSMCs and negatively with the inferred abundance of T cells and macrophages in plaques, further supporting an association between AMPA-type glutamate receptors and VSMCs in atherosclerosis." (PMID 33959644, 2021).
bipolar disorder (2 papers, 2017 to 2025). A disorder of the brain that causes unusual shifts in mood, energy, activity levels and the ability to carry out day-to-day tasks. "The Gria2 gene encodes the GluR2 subunit of the AMPA receptor, polymorphisms of which are associated with psychiatric disorders such as schizophrenia, major depressive disorder, and bipolar disorder." (PMID 40423426, 2025).
Chorea (2 papers, 2021 to 2024). Chorea (Greek for 'dance') refers to widespread arrhythmic involuntary movements of a forcible, jerky and restless fashion. "Particularly, chorea or choreoathetoid movements with an onset within the first year of age have been described in patients with GRIA2 pathogenic variants." (PMID 38921008, 2024).
colon cancer (2 papers, 2023 to 2025). "For example, GRIA2 is considered an important gene related to colon cancer staging." (PMID 40452916, 2025).
hepatocellular carcinoma (2 papers, 2014 to 2023). A malignant tumor that arises from hepatocytes. "In the current study, we demonstrate that HIF-dependent GRIA2 and GRIA3 expression in hepatocellular carcinoma and ccRCC cell lines promotes tumor progression through effects on proliferation, survival, migration and invasion." (PMID 25326682, 2014). "We next analyzed the prognostic implication of the HIF regulated genes involved in glutamate signaling in hepatocellular carcinoma (SLC1A1, SLC1A3, GRIA2, GRIA3 and FYN) using PROGgene to analyze the GSE 10141 mRNA expression data set from 80 surgically resected hepatomas." (PMID 25326682, 2014).
Huntington disease (2 papers, 2020 to 2025). Huntington disease (HD) is a rare neurodegenerative disorder of the central nervous system characterized by unwanted choreatic movements, behavioral and psychiatric disturbances and dementia. "Our findings suggest that five genes (SETDB1, TWIST1, HDAC1, SP1, and GRIA2) are likely involved in the dystropic relationship observed between Huntington’s disease and non–small cell lung cancer." (PMID 40843670, 2025).
Hypertension (2 papers, 2020 to 2022). The presence of chronic increased pressure in the systemic arterial system. "To distinguish between these two possibilities, we examined the effect of hypertension in a double mutant mouse line in which the enzyme responsible for RNA editing of GluA2, ADAR2, has been knockout out (MMRRC; Adarb1:Gria2, here abbreviated GluA2R/R)." (PMID 32792936, 2020). "Hypothalamic AMPARs facilitate autonomic responses to stressors, such as increases in blood pressure, where the enrichment of PVN neurons with AMPARs lacking GRIA2 increases excitability related to hypertension." (PMID 35888164, 2022).
malignant glioma (2 papers, 2018 to 2021). A grade III or grade IV glioma arising from the central nervous system. "The reduced GRIA2 editing at Q607R site has been observed in malignant gliomas, and the unedited GRIA2 protein promotes cell migration and invasion in these cell lines." (PMID 30524204, 2018).
tauopathy (2 papers, 2019 to 2022). Neurodegenerative disorders involving deposition of abnormal tau protein isoforms (tau proteins) in neurons and glial cells in the brain. "While this result does not demonstrate a direct role for TIA1 in mediating alternative splicing of Gria2, Snap25, or Camk2b, the results indicate that normalization of splicing represents a clear component of the neuroprotection provided by TIA1 reduction in tauopathy." (PMID 31875547, 2019).
Tremor (2 papers, 2017 to 2021). An unintentional, oscillating to-and-fro muscle movement about a joint axis. "Gria2/3 double KOs were reported also to develop tremor, starting in the second postnatal week." (PMID 28608780, 2017). "Gria3null2–/– mice were viable and survived into adulthood without neurological signs, suggesting that the tremor reported in Gria2/3 germline KO mice was not related to impaired AMPAR signalling in OL lineage cells." (PMID 28608780, 2017).
Uterine leiomyoma (2 papers, 2014 to 2022). The presence of a leiomyoma of the uterus. "For instance, Gria2 expression was found to increase in uterine leiomyoma and gastrointestinal neuroendocrine carcinoma in comparison to normal tissues." (PMID 35263365, 2022). "GRIA2 expression is upregulated in uterine leiomyoma and gastrointestinal neuroendocrine carcinoma compared to adjacent normal tissues." (PMID 25326682, 2014).
adenoma (1 paper, 2020). A neoplasm arising from the epithelium. "Finally, TSH adenomas showed 68 genes that could be regulated by methylation including SSTR2, GRIA2 and LINC01173." (PMID 33168897, 2020). "More specifically, genes with such a therapeutic potential in non-functioning adenomas included CACNA2D4, IDH1, AURKB, GRIA2, PTGS2 and CX3CR1." (PMID 33168897, 2020). "The expression of genes such as CACNA2D4, GRIA2, miR4774, miR1179 and LINC01351 was found to be up-regulated due to lower methylation rates in non-functioning adenomas." (PMID 33168897, 2020).
Arthritis (1 paper, 2017). Inflammation of a joint. "The expression of Gria1 and Gria2 encoding the glutamate receptors GluR1 and GluR2, as well as NMDA subunits (NR1, NR2A and NR2B) was relatively unaffected by arthritis." (PMID 28321113, 2017).
Auditory hallucination (1 paper, 2025). Perception of sounds without auditory stimulus. "In our study, glutamatergic neurotransmitter pathways were associated with auditory hallucinations, including the APP and GRIA2 genes." (PMID 40943654, 2025).
Brain atrophy (1 paper, 2021). Partial or complete wasting (loss) of brain tissue that was once present. "Some patients with GRIA2 variants also display progressive brain atrophy (mainly cerebellar) and white matter anomalies." (PMID 34768579, 2021).
Cerebral atrophy (1 paper, 2020). Atrophy (wasting, decrease in size of cells or tissue) affecting the cerebrum. "Overall, the findings of both congenital neuroimaging features such as under‐opercularization and thin corpus callosum and progressive features such as cerebral atrophy suggest that GRM7‐related disorders are both congenital and progressive in nature similar to that seen in GRIA2‐related NDDs." (PMID 32286009, 2020).
Diabetes (1 paper, 2013). "In contrast, diabetes did not alter the expression of GRIA2 and GRIA3 flip at either 4 or 12 weeks (p>0.02)." (PMID 23878504, 2013). "Diabetes did not change GRIA2 and GRIA3 mRNA expression possibly because photoreceptors, bipolar cells, and amacrine cells were less likely to be affected by glutamate excitotoxicity than ganglion cells." (PMID 23878504, 2013). "In this study, diabetes did not change the expression of GRIA2 and GRIA3." (PMID 23878504, 2013).
dyslipidemia (1 paper, 2025). "In an atherosclerotic rat carotid artery injury model, administration of XML or transplantation of Gria2‐overexpressing EPCs ameliorated dyslipidemia and reduced oxidative stress, markers of cellular senescence and cellular DNA damage." (PMID 40638555, 2025).
gastric cancer (1 paper, 2026). A primary or metastatic malignant neoplasm involving the stomach. "GRIA2 promotes gastric cancer cell migration, invasion, stemness, and adhesion to mesothelial cells in a glutamate-dependent manner." (PMID 41806318, 2026).
Headache (1 paper, 2022). Cephalgia, or pain sensed in various parts of the head, not confined to the area of distribution of any nerve. "GRIA2 and NR3C1, involved in glutamate and glucocorticoid signalling, respectively, appear to be specific to the headache phase in our data set." (PMID 36050647, 2022).
language disorder (1 paper, 2021). A category of disorders characterized by an impairment in the development of an individual's language capabilities, which is in contrast to his/her non-verbal intellect. "Neurodevelopmental disorders with language disorders and behavioral abnormalities (NEDLIB, OMIM#618917) are caused by heterozygous mutations in the glutamate ionotropic receptor AMPA type subunit 2 (GRIA2) gene on chromosome 4q32." (PMID 34899870, 2021).
medulloblastoma (1 paper, 2020). A malignant, invasive embryonal neoplasm arising from the cerebellum. "Unexpectedly, the expression of STMN2 and GRIA2 was comparable in the medulloblastoma subtypes compared to the normal cerebellum, apart from the GRIA2 expression (p < 0.001) in the WNT and Group 3 subtypes." (PMID 32720471, 2020).
melanoma (1 paper, 2014). A malignant, usually aggressive tumor composed of atypical, neoplastic melanocytes. "The particular nuclear localization of GRIA2 that we found in brain metastasis from both animal model and patient material may define its signaling specificity in melanoma brain metastasis, which requires further investigation." (PMID 25593989, 2014).
nicotine addiction (1 paper, 2024). "Most notably, the top biological process GO:0004971 (AMPA glutamate receptor activity) was associated with the GRIA2 gene for acetate, and nicotine addiction was the most enriched KEGG pathway." (PMID 38892420, 2024).
Parkinsonism (1 paper, 2021). Characteristic neurologic anomaly resulting from degeneration of dopamine-generating cells in the substantia nigra, a region of the midbrain, characterized clinically by shaking, rigidity, slowness of movement and difficulty with walking and gait.
pituitary adenomas (1 paper, 2020). "Druggable genes shared by all types of pituitary adenomas included NRG1, KCNA4, NCAM1, GRIA2 and GRM8." (PMID 33168897, 2020).
renal cell carcinoma (1 paper, 2022). "When looking at the top 10 upregulated genes, we found for example Ccdc180, Col11a1, Gria2, or Prdm6 in males in relation to regulation of transcription, renal cell carcinoma, and fibrosis." (PMID 35230975, 2022).
soft tissue tumors (1 paper, 2015). "IHC of the diagnostic markers STAT6 and GRIA2 would be important in differentiating SFT from other soft tissue tumors." (PMID 26337721, 2015).
tumor (22 papers, 2014 to 2025). "The gene GRIA2 is a member of a family of glutamate receptors, and its expression has been linked to the modulation of both tumor and immune cell function." (PMID 34189853, 2021). "Here, a reduced ADAR2 activity decreased the editing ratio at the Q/R site in subunit 2 of the ionotropic AMPA glutamate receptor (GRIA2, also known as GluA2 and GluR-B) transcript, which was shown to be associated with tumor progression." (PMID 30585209, 2018). "Studies have revealed that amongst the 6 identified target genes, Dpp6 and Pcdh9 were Tumor suppressor genes (TSGs) and Avpr2, Cyp4a12b, Dpp6, Gria2, Pcdh9 and Tspan11 were key tumor-related transcripts that can regulate various pathways during carcinogenesis." (PMID 35263365, 2022). "In glioblastoma, the reduction of GRIA2 transcript editing leads to cell migration and tumor invasion." (PMID 34899345, 2021). "Overexpression of ADAR3 inhibits the RNA editing of the GRIA2 Q/R site, thus inhibiting tumor migration." (PMID 34899345, 2021). "Abnormal GRIA2 expression has also been demonstrated in several tumors and tumor cell lines and is thought to mediate increased cell proliferation." (PMID 34504438, 2021). "Collectively, these results indicated that the low expression of ADAR3 may induce unedited GRIA2 transcripts level which can promote cell migration and tumor invasion." (PMID 30524204, 2018). "Previously reported editing events in GRIA2, AZIN1, and COG3 are thought to promote adult tumor progression based on functional cell viability assays." (PMID 34789196, 2021). "After searching the database to review the literature about the tumor process according to the results of GO functional and pathway annotation of DE-S-Exo-miRNA target genes, 3 apoptosis genes (NTS, CDH2 and GRIA2) were identified." (PMID 30278585, 2018). "IHC revealed that the tumor diffusely expressed CD34, CD99, Bcl2, PAX8, NAB2, STAT6, and GRIA2." (PMID 26337721, 2015).